AHR (aryl hydrocarbon receptor)
Diseases named in the same sentence as AHR in open-access papers (continued):
Sharing a sentence is not in itself a finding about the gene and the disease.
breast carcinoma (continued). "In addition, AHR has been shown to be important for normal development and physiological homeostasis and is essential for certain functions of the immune response, such as regulation of interleukin-17 producing T-helper cells and induction of the cytokine interleukin-6 in MCF7 breast cancer cells." (PMID 22235307, 2012). "However, the AHR can bind to other transcription factors, and in non-canonical pathways exerts activities which are compatible with the effects of tranilast and relevant to breast cancer therapy." (PMID 21072210, 2010). "Because some current breast cancer therapeutics are ineffective in estrogen receptor (ER) negative tumors and since the AhR may be involved in breast cancer proliferation, the effects of galangin on the proliferation of an ER-, AhRhigh line, Hs578T, were studied." (PMID 16569260, 2006). "Both cell lines are routinely used as breast cancer models, but their sensitivity to RBN2397, as well as the responsiveness of their AHR and STING-induced IFN-I signalling pathways have not been described." (PMID 41432900, 2025). "In the absence of ligand, AHR complexed with cyclin D and the cyclin-dependent kinases CDK4/6 to promote cell cycle progression in human breast cancer cells." (PMID 38982523, 2024). "This is the first report to reveal the differential effects of palmatine and jatrorrhizine at non-cytotoxic concentrations on AhR activation and CYP1 regulation in breast cancer cells." (PMID 29143794, 2017). "In human breast cancer cell lines, higher CYP1B1 expression over CYP1A1 has been related to higher AhR expression and ERα-negative status." (PMID 26715507, 2015). "Here, we demonstrate that two ERα-negative human breast cancer cell lines, MDA-MB-468 and Cal51, exhibit sensitivity to AF, and the sensitivity is retained after knockdown of AhR protein." (PMID 24885022, 2014). "By contrast, in AFP464-resistant ERα-negative basal B subtype breast cancer cell lines (Hs578T and MDA-MB-231), AhR was either undetectable at the protein level (e.g., Hs578T) or predominantly localized in the nucleus (e.g., MDA-MB-231)." (PMID 24058584, 2013). "AHR-dependent COX2 induction was also shown to play a role in blocking apoptosis induced by UVB irradiation, Adriamycin, or the dual tyrosine kinase inhibitor Lapatinib in breast cancer cells, or in non-transformed, AHR-transfected breast epithelial cells." (PMID 33396563, 2020). "Therefore, we compared the expression of BRCA-1 and AhR in human ERα-positive MCF-7, and ERα-negative UACC-3199 sporadic, breast cancer cells." (PMID 26715507, 2015). "Overall, these cell culture studies implied that the effects of αNF, selected as a prototype AhR antagonist, were influenced by cell-context and ERα status, i.e. αNF rescued BRCA-1 and ERα expression in sporadic and ERα-negative UACC-3199 breast cancer cells carrying hypermethylated BRCA-1." (PMID 26715507, 2015). "However, in human MCF-7 breast cancer cells, TSA did not affect constitutive AHR expression levels." (PMID 37696456, 2023). "Also, we tested in human estrogen receptor (ER)α-negative sporadic UACC-3199 and ERα-positive MCF-7 breast cancer cells carrying respectively, hyper- and hypomethylated BRCA-1 gene, if the treatment with the AhR antagonist α-naphthoflavone (αNF) modulated BRCA-1 and ERα expression." (PMID 26715507, 2015).
hepatoma (149 papers, 2006 to 2025). "An AhR-deficient mouse hepatoma cell line showed a loss of the mRNA expression of NRF2, thereby implying that the ARE-NRF2 element is located downstream of the AhR-ARE pathway." (PMID 37571283, 2023). "Mice fed ω3-rich or ω6-rich diets were treated with TCDD and injected subcutaneously with AHR-competent Hepa1-GFP hepatoma cells or AHR-deficient LLC lung cancer cells." (PMID 32398692, 2020). "It is reported that AHR functioned in cell cycle regulation and was implicated in hepatoma carcinogenesis." (PMID 27509054, 2016). "For instance, AhR-deficient hepatoma cells exhibited impaired activation of Akt and enhanced sensitivity to apoptosis." (PMID 25625591, 2015). "Mouse hepatoma cells deficient in AhR showed decrease proliferation resulting from a prolonged G1 phase." (PMID 25068070, 2013). "An AHRd-expressing cell line was generated by stably transfecting the AHRd cDNA into the rat hepatoma AHR-deficient cell line, BP8." (PMID 22970246, 2012). "In this study, we used DNA micorarray analysis to elucidate the profile of genes responsive to the expression of unliganded AhR by re-introducing AhR into an AhR-deficient mouse derivative (c19) of the mouse hepatoma cell line Hepa1c1c7." (PMID 19936078, 2007). "Similarly, in hepatocellular carcinoma, the development of lenvatinib resistance is closely associated with the aberrant activation of the AHR-AREG-EGFR-ERK1/2-Cyclin D1 signaling axis." (PMID 41585883, 2025). "AhR has long been associated with a variety of cancers, and its expression is elevated and the receptor chronically active in tumors, including T cell leukemia, B cell lymphoma, hepatocellular carcinoma, glioblastoma, and lung cancer, among others." (PMID 38339226, 2024). "Furthermore, TCDD has been shown to decrease mitochondrial respiration in mouse hepatoma cells, and the basal oxygen consumption rate appears to be lower in AhR-deficient cells, which seems to support our observations." (PMID 36077780, 2022). "Moreover, one of these studies performed in two mouse hepatoma cell lines showed that TCDD was able to rapidly decrease mitochondrial respiration in AhR-expressing cells while this effect was almost abolished in AhR-deficient cells." (PMID 30147834, 2018). "Genome-wide ChIP/chip analysis using wild type Hepa-1c1c7 mouse hepatocellular carcinoma cells and its AhR-deficient c37 derivative, have identified gene clusters regulated by AhR with a suspected implication in cell differentiation, patterning and development under basal cell conditions." (PMID 27243009, 2016). "We examined the expression kinetics of some of the aryl hydrocarbon receptor (AhR)-regulated genes in LA1 variant cells compared to wild type (WT) Hepa-1 mouse hepatoma cell lines, and we investigated the stability of AhR protein as a key step in the function of this receptor." (PMID 25637755, 2015). "Furthermore, it has been shown that changes in mRNA expression of specific genes in the AHR pathway are linked to progression of HCV-associated hepatocellular carcinoma." (PMID 19821982, 2009). "In another study, activation of the aryl hydrocarbon receptor (AhR) by OPFRs was investigated using the reporter rat hepatoma cell line H4IIE-CALUX." (PMID 40278613, 2025). "Hexachlorobenzene activates the ERK1/2 signaling pathway in an AhR-dependent manner, upregulates the expression of the cell cycle protein Cyclin D1, and promotes the proliferation of hepatocellular carcinoma cells and hepatic preneoplastic lesions." (PMID 41585883, 2025). "The AhR exhibits a complex and context-dependent dual role in the development and progression of hepatocellular carcinoma (HCC), with its function varying significantly across different tumor stages." (PMID 41585883, 2025). "The CAFLUX system enabled real-time visualization of AhR-mediated transcriptional activity in human hepatocellular carcinoma cells." (PMID 41155323, 2025).
hepatoma (continued). "In summary, these AHR-dysregulated lncRNAs offer valuable insights into the molecular mechanisms of hepatocellular carcinoma and present potential targets for future therapeutic strategies." (PMID 40248203, 2025). "Although most reports suggest a pro-tumorigenic function for AhR in hepatocellular carcinoma, some studies have documented a tumor suppressive role." (PMID 38807762, 2024). "TDO 2 regulates metastasis and invasion of hepatocellular carcinoma by activating the Kyn-AhR pathway to promote EMT in cancer cells." (PMID 38434684, 2024). "KMP showed inhibitory effects against aryl hydrocarbon receptor (AHR)- and nuclear factor erythroid 2-related factor 2 (Nrf2)-induced expression of the drug-metabolizing enzyme in hepatocellular carcinoma." (PMID 38339336, 2024). "Recent analysis suggests that HCV-induced hepatocellular carcinoma tumors exhibit an increased expression of genes involved in the AhR signaling pathway." (PMID 38680494, 2024). "The researchers found that in murine hepatoma cells treated with cell-free bacterial supernatants of L. reuteri R2lc and 2010 strains, the inactivation of pks prevented AhR activation in both strains." (PMID 39517263, 2024). "Disruption of AhR function in a murine hepatoma cell line led to decreased proliferation and prolonged doubling time compared to its wild-type counterpart." (PMID 38339226, 2024). "AhR activation in hepatocellular carcinoma upregulates p27kip1, which suppresses hepatocellular carcinoma cell proliferation." (PMID 38434684, 2024). "In vitro assays conducted on murine hepatoma cell lines have shown that incubation with dexamethasone enhances AhR transcription through a GR-dependent mechanism, leading to an increased response to AhR ligands." (PMID 38283348, 2023). "Constitutive expression of AHR was induced in murine Hepa-1 hepatoma cells by the HDAC inhibitors butyrate and trichostatin A (TSA)." (PMID 37696456, 2023). "In a human hepatoma cell line incubated with PA, we found that AhR was translocated to the nucleus 15 min following the administration of AN1284." (PMID 37664863, 2023). "The expression of aryl hydrocarbon receptor (AHR) and PD-L1 was increased in HCC patients associated with aflatoxin B1 (AFB1), and anti-PD-L1 showed greater efficacy on hepatoma xenografts derived from AHR ectopic expression cells." (PMID 38155974, 2023). "Silencing AhR in the hepatoma cells confirmed that part of the direct actions of AN1284 is mediated through AhR activation." (PMID 37664863, 2023). "HDAC8 has been reported as an AHR target as it was induced by TCDD and by overexpression of AHR in hepatoma cell lines." (PMID 37696456, 2023). "One study investigated the effect of AhR agonists β-NF and TCDD on PPAR-α expression and glycolysis in murine hepatoma cell lines, Hepa1c1c7, and in AhR knockout mice." (PMID 36418969, 2022). "We evaluated the agonistic effects of individual MICTs on AHR in a stably transfected reporter human hepatoma cell line AZ-AHR after 4 h of treatment." (PMID 36142735, 2022). "In contrast, 2,3,7,8-tetrachlorodibenzo-p-dioxin (TCDD), a high affinity AhR ligand, was found to induce Nrf2 mRNA expression in an AhR-dependent manner in mouse hepatoma 1c1c7 cells, suggesting that AhR directly increased the transcription of Nrf2 mRNA." (PMID 35204110, 2022). "The pure antagonist 3-methoxy-4-nitroflavone of TCDD-induced AhR DRE binding in mouse hepatoma cells is a partial agonist in adenocarcinoma cells of guinea pigs." (PMID 34948089, 2021). "In line with our findings, rutaecarpine has been found to AhR-dependently induce the downstream gene expression in human hepatoma cells and keratinocytes." (PMID 34955744, 2021). "The enhanced AhR induction response in the H4L7.5c2 recombinant rat hepatoma cells makes them particularly useful for high-throughput screening purposes using 384-well plates, because significantly fewer cells are needed to obtain a measurable response." (PMID 33828936, 2021).
hepatoma (continued). "The molecular mechanisms of PER1 repression by AhR were determined in hepatoma cells using TCDD and beta-naphthoflavone as AhR activators." (PMID 33451129, 2021). "The ability of MICT to bind the AhR was then evaluated by competitive radio-ligand binding assay, using cytosols from mouse hepatoma cells Hepa1c1c7." (PMID 32283770, 2020). "Cigarette smoke condensate decreases mRNA expression and activity of hOCT1 in human hepatoma HepaRG cells, probably via activation of the aryl hydrocarbon receptor (AhR) signaling pathway." (PMID 33732143, 2020). "In different cancer types, AHR expression and activity negatively correlates with patient survival, including glioblastoma and hepatocellular carcinoma." (PMID 33260776, 2020). "Prothioconazole has been shown to be an inhibitor of expression of the AHR target Cyp1a1 in a mouse hepatoma cell line, while thiabendazole actived a mouse PXR-dependent reporter system in vitro." (PMID 32403288, 2020). "Both NQs induced AhR-dependent gene expression in mouse and human hepatoma cells, but were more potent and efficacious in human cells." (PMID 32526934, 2020). "Our recent in vitro studies with the active derivative of C2 proved it to have virtually equal potency in inducing CYP1A1 activity to TCDD in a rat hepatoma cell line and exhibit similar modelled binding properties to the ligand binding region of the AHR." (PMID 30893768, 2019). "Observations of the H4IIE hepatocellular carcinoma lines showed activation of the AhR and of the transcription of the CYP1A1 gene." (PMID 31681212, 2019). "It was demonstrated in rat hepatoma cells that humic substances can induce the aryl-hydrocarbon receptor." (PMID 30718974, 2019). "The nuclear receptor aryl hydrocarbon receptor (AhR) is involved in the regulation of Treg and Th17 cell differentiation, and can be activated by cannabinoids, as demonstrated in a human hepatoma cell line." (PMID 30720730, 2019). "Sinal and Bend demonstrated that the gene expression and enzymatic activity of Cyp1a1 can be modulated directly by bilirubin via an AhR pathway in mouse hepatoma cells." (PMID 29487603, 2018). "Ablation of AHR or ISX in hepatoma cells suppresses cell growth, whereas its overexpression promotes cell proliferation and leads to enhanced in vitro and in vivo tumorigenic activity." (PMID 29301348, 2018). "Immunocytochemical studies of mouse hepatomas revealed that the AhR is predominantly a cytosolic receptor under normal conditions and that the AhR relocates to the nucleus after exposure to xenobiotics, such as TCDD." (PMID 30486367, 2018). "Son and Rozman showed, in mouse hepatoma cells, that AhR activation by ligand binding induced expression of uPA protease." (PMID 29487603, 2018). "The HDAC8 promoter region between −168 and +30 bp was pulled down by the anti-AHR antibody in hepatoma cells with high HDAC8 expression." (PMID 27283490, 2017). "Taken together, these data suggest that the reduced cell viability seen in AhR expressing 5L hepatoma cells treated with analog E was most likely due to induction of apoptosis." (PMID 29194351, 2017). "The modulation regulatory effect of RB1 by HDAC 8 was finally determined in hepatoma cells with ectopic HDAC 8 expression but transfected with AHR shRNAi." (PMID 27283490, 2017). "The hepatoma cells with HDAC8 expression showed a lesser degree of enhancement (30%) of BrdU incorporation than those overexpressing AHR." (PMID 27283490, 2017). "Hepatoma cells with both AHR and HDAC8 expression showed an additive effect on cell proliferation activity." (PMID 27283490, 2017).
hepatoma (continued). "In the present study, we found that analog E inhibited hepatoma cell growth in an AhR dependent manner at a concentration of 10 μM." (PMID 29194351, 2017). "Our results provide support for continued investigation of the AhR as therapeutic for cancers such as hepatocellular carcinoma." (PMID 28424418, 2017). "Our study provides support for development of AhR-based therapeutics against cancer, especially hepatocellular carcinoma where the AhR is highly expressed." (PMID 28424418, 2017). "In conclusion, we characterized a novel anti-proliferative effect of SU5416 in hepatoma cells that strongly requires the expression of AhR." (PMID 28424418, 2017). "Our results showed that SU5416 strongly activates the AhR and Arnt signaling, which mediates its potent anti-proliferative effects in hepatoma cells." (PMID 28424418, 2017). "More than ten years ago, Barouki's lab revealed that activation of the AhR leads to induction of PON1 in human hepatoma cells as well as in vivo in mouse liver." (PMID 27829840, 2016). "Earlier studies have shown that GNF-351 inhibited AHR activation in murine hepatoma-derived reporter cells H1L1.1.1c2 with an IC50 value of 116 nM." (PMID 24417285, 2014). "Recently, we also investigated the effect of seven PFASs on AhR, and found that only PFDoA and PFDA did transactivate AhR in mouse Hepatoma cells." (PMID 24629213, 2014). "Because G-protein signaling is involved in the regulation of AhR stability, we further investigated the AhR function and its possible relationship to G-protein signaling in hepatocellular carcinoma." (PMID 25081364, 2014). "Such migration-related functions of AhR can be induced by TCDD in human hepatoma HepG2 and human breast tumor MCF-7 cells or by receptor knock-out in primary keratinocytes." (PMID 25238970, 2014). "To determine if this induction was indeed due to the translocation of AHR to the nucleus, we treated human hepatoma cells with Compounds D1–D16 and analyzed AHR localization through immunostaining." (PMID 25329374, 2014). "Our study showed that BBP promoted cell migration and invasion through the AhR/Gβ/PI3K/Akt/NF-κB pathway in hepatocellular carcinoma cells." (PMID 25081364, 2014). "PFOS and PFOA were reported to increase the CYP1A1 expression in salmon kidney and liver, and PFOS significantly further increased the TCDD-induced AhR activity in rat Hepatoma cells." (PMID 24629213, 2014). "To validate the hits identified from VLS, we first measured each compound’s ability to induce two different AHR target genes in human hepatoma cells." (PMID 25329374, 2014). "BBP affected hepatocellular carcinoma progression through the aryl hydrocarbon receptor (AhR) and that benzyl butyl phthalate (BBP) stimulated AhR at the cell surface, which then interacted with G proteins and triggered a downstream signaling cascade." (PMID 25081364, 2014). "Cellular fractionation experiments demonstrated a decreased mitochondrial pool of Mrpl40 after TCDD treatment in AHR expressing hepatoma cells." (PMID 24454361, 2013). "We utilized the wild type rat hepatoma cell line, 5L, which harbors the high affinity AHR isoform, and our newly created AHRd-15 cell line." (PMID 22970246, 2012). "To identify the duration of activity of SU5416 as a ligand of the AHR, we dosed human 101L-hepatoma cells with SU5416 at a dose of 100 nM or TCDD at 1 nM, and measured luciferase activity at 4, 24, 48, 72, and 96 hours." (PMID 22970246, 2012). "Mouse serum was applied directly to mouse hepatoma cells stably transfected with an AhR-driven enhanced green fluorescent protein (EGFP)-expressing reporter construct with a promoter similar to that in the AhR–CALUX assay." (PMID 20435556, 2010). "The induction of ERK and JNK was also noted in A-549 human lung carcinoma and Hepa-1 mouse hepatoma cells, which possess a functional AhR battery, following treatment of TCDD or B[a]P." (PMID 19531241, 2009).